CHI3L1 (chitinase 3 like 1)
Diseases named in the same sentence as CHI3L1 in open-access papers (continued):
Sharing a sentence is not in itself a finding about the gene and the disease.
colon cancer (continued). "Furthermore, in vitro experiments using the HT29 human colon cancer cell line showed that CHI3L1 elevated intracellular reactive oxygen species (ROS) in the presence of hydrogen peroxide." (PMID 40643503, 2025). "CHI3L1 specifically promotes macrophage recruitment and tumor angiogenesis in colon cancer." (PMID 38667293, 2024). "CHI3L1 significantly increases the proliferation of colon cancer cells and the secretion of IL-8 and monocyte chemoattractant protein-1 (MCP-1) by upregulating the phosphorylation of ERK1/2 and JNK and promoting the chemotaxis of macrophages to the tumor microenvironment and angiogenesis." (PMID 39068486, 2024). "Also, CHI3L1 overexpression induced autophagy in various cancer cell lines such as human liver cancer and colon cancer cell lines." (PMID 37340009, 2023). "The CHI3L1 immunohistochemistry staining in 15 colon cancer samples and corresponding adjacent normal tissues showed that CHI3L1 mainly distributed in the cytoplasm and its positive rate was much higher in cancer tissues than adjacent normal tissues (P = .005)." (PMID 31536166, 2020). "High serum levels of YKL-40 (also called Chitinase 3-like 1) are associated with CRC in subjects without comorbidities and are correlated with poor prognosis in patients with colon cancer." (PMID 33167521, 2020). "Furthermore, we analyzed the correlation of the clinicopathological characteristics with the CHI3L1 expression according to the 243 colon cancer cases downloaded from the UCSC Xena platform." (PMID 31536166, 2020). "The results of the cell proliferation curve showed that the relative proliferation rate of cells increased significantly after overexpression, which indicated that the high expression of CHI3L1 could promote the proliferation of colon cancer cells." (PMID 31536166, 2020). "CHI3L1 was overexpressed in colon cancer cell lines by lentiviral technology." (PMID 31536166, 2020). "However, the functions of CHI3L1 in colon cancer cell proliferation and its cetuximab sensitivity are still unclear." (PMID 31536166, 2020). "Inhibition of CHI3L1 using pan-chitinase inhibitors, including cyclic dipeptide CI–4 [cyclo-(I-Arg-d-Pro)], allosamidine, and methylxanthine derivatives (e.g. caffeine), effectively retard the growth and viability of colon cancer cell line." (PMID 26440614, 2015). "CHI3L1, PTPRC, and ITGAM, three key genes in colon cancer proliferation and metastasis, demonstrated the highest baseline expression and significant changes in gene expression." (PMID 38037545, 2023). "CHI3L1 does not increase ROS production in colon cancer cells (HT-29) under normal conditions; however, it increases ROS content in HT-29 cells under oxidative stress conditions." (PMID 39068486, 2024). "Additionally, CHI3L1 enhances the secretion of IL-8 and MCP-1 in colon cancer cells through signaling mediators such as ERK and JNK." (PMID 38003338, 2023). "Chitinase-3-like protein 1 (CHI3L1/YKL-40), a glycoprotein secreted by various cancer cells and stromal cells, enhances the synergic effect of syndecan-1 and β3 integrin and activation of FAK/ERK pathway in ECs to promote angiogenesis in breast and colon cancer." (PMID 36906534, 2023).
endothelial dysfunction (38 papers, 2008 to 2025). In vascular diseases, endothelial dysfunction is a systemic pathological state of the endothelium (the inner lining of blood vessels) and can be broadly defined as an imbalance between vasodilating and vasoconstricting substances produced by (or acting on) the endothelium. "Additionally, increased Chi3l1 levels are independently associated with proteinuria, cardiovascular disease, and endothelial dysfunction in renal transplant recipients." (PMID 39769202, 2024). "We hypothesize that mild inflammation and endothelial dysfunction can cause micro- and macrovascular complications that induce systemic secretion of CHI3L1." (PMID 38110934, 2023). "CHI3L1, also known as YKL-40, encodes an inflammatory glycoprotein involved in endothelial dysfunction and cardiovascular disease." (PMID 26248552, 2015). "CHI3L1 plasma levels in Type II diabetes patients are positively correlated with insulin resistance and endothelial dysfunction." (PMID 18554398, 2008). "For example, endothelial dysfunction may function in the pathogenesis of male idiopathic infertility, while Chi3l1 levels are increased and act as markers for endothelial dysfunction in male patients with idiopathic infertility." (PMID 39769202, 2024). "Chitinase-3-like protein 1 (CHI3L1/YKL-40) belongs to the chitinase family and is involved in endothelial dysfunction and tissue remodeling." (PMID 40873950, 2025).
pulmonary fibrosis (37 papers, 2015 to 2025). Chronic progressive interstitial lung disorder characterized by the replacement of the lung tissue by connective tissue, leading to progressive dyspnea, respiratory failure, or right heart failure. "Chi3l1 has been implicated in pulmonary fibrosis and is expressed in lung alveolar macrophages and regulates inflammation, cell proliferation and apoptosis in connective tissue cells including fibroblasts." (PMID 38481391, 2023). "Recently, increasing number of studies are demonstrating that chitinase and chitinase like proteins (C/CLPs) represented by CHIT1 and CHI3L1 are significantly implicated in the pathogenesis of various human diseases including pulmonary fibrosis." (PMID 35370755, 2022). "To investigate the role of CHI3L1 in PH associated with pulmonary fibrosis, we examined the effect of CHI3L1 expression on PH responses in the bleomycin mouse model of pulmonary fibrosis." (PMID 35951428, 2022). "Our findings demonstrate that ILC2-mediated, CRTH2-dependent mechanism(s) contributed to optimal CHI3L1-induced amplified fibrotic responses in the bleomycin-induced pulmonary fibrosis in Hps1−/− mice." (PMID 39405112, 2024). "CHI3L1(YKL40) exhibits specific regulatory effects in some fibrotic diseases such as pulmonary fibrosis, liver cirrhosis, and heart disease." (PMID 38543093, 2024). "Nevertheless, our results indicate that CRTH2 expression on ILC2s is responsible for CHI3L1-induced recruitment and migration of ILC2s in the lung, which interact with fibroblasts and contribute to development of lung fibrosis." (PMID 39405112, 2024). "The recent findings from single-cell RNA-Seq data from mice and human lung fibrosis revealed the presence of a distinct profibrotic macrophage subtype in the fibrotic lung, with a higher level of CHI3L1, CHIT1, APOE, and integrins." (PMID 36626225, 2023). "The study demonstrated that the interaction between chitinase-3-like 1 (CHI3L1) and CRTH2 promotes pulmonary fibrosis, while CRTH2 deficiency is protective." (PMID 37681924, 2023). "In idiopathic pulmonary fibrosis models, CHI3L1 demonstrated to be crucial for the accumulation of CD206+ macrophages that subsequently induce fibroblastic proliferation and survival." (PMID 37166517, 2023). "Murine bleomycin lung fibrosis model showed a predominant shift toward alternative macrophage activation in CHI3L1 overexpressing Tg mice, and eradication of these profibrotic macrophages is sufficient to reduce tissue fibrosis." (PMID 35370755, 2022). "CHI3L1 plays a critical role in vascular remodeling responses in a bleomycin-induced pulmonary fibrosis model." (PMID 35951428, 2022). "ChIT1 and CHI3L1 distinctly contribute to pulmonary fibrosis using unique receptors or interacting molecules and signaling pathways." (PMID 35370755, 2022). "Studies from our laboratory and others demonstrated that circulating levels of CHI3L1 are higher in individuals with tissue injury and remodeling, including PH and pulmonary fibrosis." (PMID 35951428, 2022). "With these limitations in mind, here the molecular and mechanistic implications of CHIT1 and CHI3L1 as potential therapeutic targets are discussed based on up-to-dated and common lung pathologies of pulmonary fibrosis." (PMID 35370755, 2022). "In this review, we will discuss specific roles and regulatory mechanisms of CHIT1 and CHI3L1 in profibrotic cell and tissue responses as novel therapeutic targets of pulmonary fibrosis." (PMID 35370755, 2022). "A substantial body of literatures are strongly support that both CHIT1 and CHI3L1 contribute to the development and progression of pulmonary fibrosis through regulation of profibrotic macrophage activation and/or invasive myofibroblast differentiation." (PMID 35370755, 2022). "It was reported that the CD44, a putative receptor for CHI3L1, mediates invasive fibroblasts phenotypes leading to severe lung fibrosis." (PMID 35370755, 2022).
pulmonary fibrosis (continued). "Dysregulated expression of CHIT1 and CHI3L1 was noted in the patients with pulmonary fibrosis and their levels were inversely correlated with clinical outcome of the patients." (PMID 35370755, 2022). "High levels of Chitinase-3-like 1 (CHI3L1), a prototypic chitinase-like protein, have been associated with tissue injury and remodeling in various forms of pulmonary fibrosis (PF), including HPS-PF." (PMID 33841163, 2021). "It was also reported that Chi3L1 is increased in serum and lung of patients suffering from idiopathic pulmonary fibrosis, and high serum Chi3L1 level in patients with small cell lung cancer is related to early death." (PMID 32127023, 2020). "Phenotypic analyses using CHI3L1 knockout (KO) mice, overexpression models, and anti-CHI3L1 antibody interventions in both acute and chronic inflammatory conditions, such as allergic inflammation, colitis, and pulmonary fibrosis, have yielded critical insights." (PMID 40643503, 2025). "In both models, depletion of ILC2s significantly diminished fibrosis development in the Hps1−/− mice, suggesting that ILC2-mediated mechanisms contributed to optimal CHI3L1-induced amplified fibrotic responses in the bleomycin-induced pulmonary fibrosis in Hps1−/− mice." (PMID 39405112, 2024). "In patients with HPS pulmonary fibrosis (HPSPF) and idiopathic pulmonary fibrosis (IPF), high serum and lung levels of CHI3L1 are associated with disease progression and with alternatively activated circulating monocytes and macrophages, independent of its ability to bind and degrade chitin." (PMID 39405112, 2024). "However, the specific roles of CD44, heparin-like molecules, and hyaluronic acid and their interactions with CHI3L1 in the pathogenesis of pulmonary fibrosis remain to be determined." (PMID 35370755, 2022). "Notably, dysregulated expression of CHIT1 and CHI3L1 was noted in the patients with pulmonary fibrosis and their levels were inversely correlated with clinical outcome of the patients." (PMID 35370755, 2022). "In HPS, levels of CHI3L1 are higher in patients with HPS-PF in comparison with patients without pulmonary fibrosis, where higher levels are associated with greater disease severity." (PMID 33841163, 2021). "However, CHIT1 and CHI3L1 also have similar regulatory functions in the development of profibrotic macrophage activation, fibroblasts proliferation and myofibroblasts differentiation, the major hallmarks of pulmonary fibrosis." (PMID 35370755, 2022). "Chitinase-3-like protein 1 (CHI3L1, YKL-40 protein) is a glycoprotein that plays a role in numerous diseases, such as arthritis, idiopathic pulmonary fibrosis, and liver diseases." (PMID 38304922, 2024). "In contrast to the control mice, mice with pulmonary fibrosis exhibited notably higher levels of lung proteins such as TGF-βR2, SKP-1, CHI3L1, OGG1, and Galectin-3, alongside lower expression of p-4Ebp1, SARA, p-P70S6K, and PP2A." (PMID 38259493, 2023). "Here we will overview the recent progress that revealed a new paradigm on the pathogenesis of pulmonary fibrosis and will discuss a new therapeutic strategy by targeting both CHIT1 and CHI3L1." (PMID 35370755, 2022). "M2 polarization can be induced by the microenvironment shaped by Th2 polarization and promotes pulmonary fibrosis through the production of TGF-β, CCL18, chitinase 3-like 1 (CHI3L1), MMPs, and activation of the Wnt/β-catenin pathway." (PMID 35721111, 2022). "Interestingly, the non-enzymatic chitinase 3-like 1 has been implicated in the inflammatory response to respiratory virus infection where it is elevated in the inflammatory phase, and in the fibroproliferative phase in mouse models of pulmonary fibrosis." (PMID 35354473, 2022). "Preclinical studies using animal model of pulmonary fibrosis further demonstrated that both CHIT1 and CHI3L1 are sufficient and required for fibroproliferative responses." (PMID 35370755, 2022).
pulmonary fibrosis (continued). "Although the mechanism or the pathways that CHIT1 and CHI3L1 use to regulate pulmonary fibrosis have not been fully understood yet, these studies identify CHIT1 and CHI3L1 as significant modulators of fibroproliferative responses leading to persistent and progressive pulmonary fibrosis." (PMID 35370755, 2022). "Moreover, a previous study confirmed the predicted emergence of CHI3L1- and SPP1- positive alveolar macrophages and increased CHI3L1 expression in AT2 cells in patients with pulmonary fibrosis." (PMID 35737303, 2022). "For instance, patients with idiopathic pulmonary fibrosis (IPF) showed significant CHI3L1 expression in the lungs, but when these patients experienced acute exacerbations, CHI3L1 expression dropped to a level between those of IPF patients and the control group." (PMID 26431492, 2015). "Interestingly, the severity of pulmonary fibrosis in CHI3L1-null mice treated with bleomycin was not reduced compared with WT mice, suggesting that lower severity of PH observed in these mice was not the result of a reduction in lung fibrosis." (PMID 35951428, 2022).
type 2 diabetes (37 papers, 2007 to 2025). "Previous studies have shown that elevated serum CHI3L1 levels have been found in cardiovascular disease, type 1 diabetes and type 2 diabetes and several types of cancer." (PMID 40731875, 2025). "After merging and filtering across datasets, 13 genes were found to be consistently upregulated in both ulcerative colitis and type 2 diabetes, with CXCL9, S100A8, CXCL10, CHI3L1, and SLC6A14 showing the most significant alterations." (PMID 41155631, 2025).
Insulin resistance (36 papers, 2007 to 2025). Increased resistance towards insulin, that is, diminished effectiveness of insulin in reducing blood glucose levels. "Elevated serum levels of CHI3L1 are a hallmark of metabolic syndrome, intimately linked to insulin resistance and leptin dysregulation." (PMID 41463897, 2025). "This is consistent with a previous study in which elevated CHI3L1 levels were associated with insulin resistance in patients with T2D28." (PMID 41462520, 2025). "The WT C57BL/6 develop NAFLD/NASH like pathology on HFD in association with enhanced Chi3L1 gene expression levels which allowed us to access the role of this gene in the pathogenesis of insulin resistance." (PMID 33498326, 2021). "In this context, serum levels of Chi3L1 may be linked to insulin resistance and obesity." (PMID 33498326, 2021). "In GDM patients, Chi3l1 levels are correlated with glycated hemoglobin, fasting insulin, and homeostasis model assessment of insulin resistance (HOMA-IR)." (PMID 39769202, 2024). "Additionally, Chi3l1 can markedly blunt hepatic insulin signaling as measured by reduced pAKT, pGSK-3β, and pERK levels in NAFLD, suggesting that Chi3l1 may play a role in the development of hepatic insulin resistance associated with inflammation and lipid deposition." (PMID 39769202, 2024). "Plasma CHI3L1 levels in T2D patients are positively correlated with insulin resistance and blood lipid abnormalities, and CHI3L1 levels were 50% higher than the median in a control group." (PMID 38003338, 2023). "To investigate the effects of Chi3L1 expression on hepatic insulin resistance, we fed WT mice in group 1 with CD, while groups 2 to 5 were fed with HFD to induce hepatosteatosis." (PMID 33498326, 2021). "In this context, we have evaluated the role of Chi3L1 in the development of insulin resistance by comparing insulin signaling in a Chi3L1 KO murine model to wild type (WT) mice C57BL/6 fed a CD." (PMID 33498326, 2021). "Germane to disordered metabolism in DMD, CHI3L1 also counteracts TNFα-induced insulin resistance in muscle cells." (PMID 29554127, 2018). "Furthermore, CHI3L1 (Chitinase-3-like protein 1) and CD36 are associated with associated with insulin resistance, T2D, and CVD." (PMID 39859066, 2025). "Overexpression induced by HFD may contribute to the lipid deposition and targeting Chi3L1 function or reducing its level may improve insulin resistance and reduce steatohepatitis." (PMID 33498326, 2021). "We hypothesize that Chi3L1 gene expression is important in the development of hepatic insulin resistance characterized by the generation of pAKT, pGSK, and pERK in wild type and Chi3L1 knockout (KO) murine liver following insulin stimulation." (PMID 33498326, 2021). "Therefore, Chi3L1 gene is highly expressed in both human and murine liver with NAFLD/NASH histology and all three anti-Chi3L1 mAb proteins, to variable degrees, inhibit its function in vivo and substantially improve hepatic insulin resistance following 16 weeks of anti-Chi3L1 mAb treatment." (PMID 33498326, 2021). "Although a few studies have identified correlations between Chi3L1 and insulin resistance, dyslipidemia, and acute infections, much remains unknown about the mechanism of Chi3L1 in inflammation and metabolic homeostasis, particularly in the setting of HIV/AIDS." (PMID 29746485, 2018).